MIRLET7G (microRNA let-7g)
Synonyms: hsa-let-7g; LET7G; MIRNLET7G; let-7g
Gene: MicroRNA gene on chromosome 3 (52,268,278 to 52,268,361, reverse strand). Ensembl gene ENSG00000199150.
Gene Ontology:
Biological process: miRNA-mediated post-transcriptional gene silencing
Cellular component: RISC complex
Homologues: Orthologues: chimpanzee ptr-let-7g (100% identical), dog MIRLET7G (100% identical), macaque MIRLET7G (100% identical), mouse Mirlet7g (100% identical), pig MIRLET7G (100% identical), rabbit MIRLET7G (100% identical), rat Mirlet7g (100% identical), guinea pig MIRLET7G (99% identical), tropical clawed frog xtr-let-7g (87% identical), zebrafish mirlet7j (81% identical). Paralogues in human: MIRLET7F1 (70% identical), MIRLET7F2 (69% identical), MIRLET7A1 (67% identical), MIRLET7I (67% identical), MIRLET7A3 (64% identical), MIRLET7A2 (60% identical), MIR98 (58% identical), MIRLET7D (58% identical), MIRLET7C (55% identical), MIRLET7E (55% identical).
Diseases named in the same sentence as MIRLET7G in open-access papers:
MIRLET7G is named in the same sentence as 3 diseases in open-access papers, as found by Europe PMC text mining. Sharing a sentence is not in itself a finding about the gene and the disease. The quoted sentences say what the papers report.
mammary tumor (1 paper, 2022). "Similarly, several exosome-derived miRNA orthologs previously reported for increased expression in both canine and human mammary tumor cell lines, including MIR21, MIR106B, MIR181A1, MIR183, MIR200B, and MIRLET7G, were presented." (PMID 35765483, 2022).
MIRLET7G also shares sentences with these, for which no sentence is quoted: emphysema (1 paper); teratospermia (1).